SMARCA4 (SWI/SNF related BAF chromatin remodeling complex subunit ATPase 4)
Diseases named in the same sentence as SMARCA4 in open-access papers (continued):
Sharing a sentence is not in itself a finding about the gene and the disease.
glioblastoma (10 papers, 2016 to 2025). The most malignant astrocytic tumor (WHO grade IV). "Similarly, as found in adult glioblastomas, CRISPR-based LOF and pharmacologic inhibition of SMARCA4 revealed that SMARCA4 is required to maintain characteristics of H3K27M-driven diffuse midline glioma (DMG)." (PMID 40599851, 2025).
ovarian tumors (10 papers, 2015 to 2026). "Some lung and ovarian tumors are connected to the loss of expression of SMARCA4 gene." (PMID 31676783, 2019). "This case report emphasizes the importance of performing INI1/SMARCB1 IHC on undifferentiated ovarian tumors in young patients that show a retained SMARCA4 expression to determine the correct diagnosis of SCCOHT." (PMID 35200537, 2022). "The third study demonstrated loss of SMARCA4 protein in 14/17 SSCOHT and only 2/485 other primary ovarian tumors (0.4%)." (PMID 32149361, 2020). "We determined the sensitivity and specificity of SMARCA4 IHC in differentiating SCCOHT from other difficult to characterise ovarian tumours that can mimic SCCOHT (sex cord, germ cell, small cell sarcomatous, blastemal and undifferentiated tumours)." (PMID 31844183, 2020). "Previous studies have described the value of SMARCA4 IHC to differentiate SCCOHT from ovarian neoplasms (ON), with similar histologic appearances." (PMID 31844183, 2020). "Hence, the chemotherapy regimens for patients with ovarian tumors with SMARCA4 expression deletion have a specific reference value." (PMID 40826772, 2025). "In most prior studies, the primary diagnosis of SSCOHT was based on morphology, which can mimic a large variety of other ovarian tumors, and testing for SMARCA4 or BRG1 was done only retrospectively in morphologically diagnosed cases." (PMID 32149361, 2020). "We aimed to evaluate the clinical utility of SMARCA4 IHC testing among a large cohort of centrally reviewed SCCOHT (N = 44) and other rare ovarian tumours occurring in young women and frequently misdiagnosed as SCCOHT (N = 94)." (PMID 31844183, 2020).
rhabdoid tumor predisposition syndrome (10 papers, 2015 to 2026). "Truncating variants in SMARCA4 have been associated with rhabdoid tumors predisposition syndrome, a group of rare and aggressive tumors occurring predominantly in infancy." (PMID 41568967, 2026). "Preserved INI1 protein expression and a SMARCA4 mutation were also observed in familial rhabdoid tumor predisposition syndrome (RTPS), which has been linked to heterozygous SMARCB1 germline mutations." (PMID 26109171, 2015). "SCCOHT bears great resemblance to malignant rhabdoid tumors at other sites, and is seen in patients with rhabdoid tumor predisposition syndrome (RTPS; generally type 2 with germline mutations in SMARCA4)." (PMID 39847050, 2025). "The rhabdoid tumor predisposition syndrome is rarely as a consequence of the loss of the expression of the ATPase subunit SMARCA4, also known as BRG1, another SWI/SNF chromatin-remodeling complex member." (PMID 34777208, 2021).
viral infection (10 papers, 2014 to 2025). "PBRM1 is a chromatin modulator of the SWI/SNF chromatin remodeling complex, which includes SMARCA4, SMARCB1, SMARCC1, ARID1A, DPF2, and SMARCE1, also implicated in ACE2 expression regulation and, thus, in host cell susceptibility to viral infection." (PMID 40378209, 2025). "Using brilliant databases and bioinformatics tools, we identified GABBR1-centered ceRNAs formed by PDGFRB and WNT2B via hsa-miR-19-3p and RNA-RNA interactions with HMGA1 and SMARCA4 as shared molecules between diabetes and viral infection." (PMID 37969011, 2023). "Mutations in SMARCA4 may disrupt mSWI/SNF complex function, resulting in lower ACE2 levels and potentially reducing cellular susceptibility to viral infection." (PMID 40034745, 2025). "Notably, a number of additional genes localized to SMARCA4-dependent genomic regions were those found to mediate viral infection in our CRISPR screen along with ACE2, such as SLC4A4 and HNF1A, thus suggesting that mSWI/SNF complexes regulate a coronavirus susceptibility gene expression axis." (PMID 36894709, 2023). "Overexpression of JAK1, TYK2, MAP2K1, IFNG, TRPM2, and ADCY9 significantly inhibited viral infection, whereas overexpression of SNX27, GATA4, EHMT2, PCBP2, SMARCA4, and SLX4 enhanced viral infection." (PMID 40530850, 2025). "On the basis of these results, we achieved a shared interRNA mechanism between diabetes and viral infections, which consisted of GABBR1, HMGA1, and SMARCA4." (PMID 37969011, 2023).
breast tumors (9 papers, 2013 to 2021). "Analyses of human breast tumors indicate that SOX4 mRNA is uniformly overexpressed in basal-like tumors relative to adjacent normal tissue along with the SWI/SNF catalytic subunit SMARCA4 and SMARCB1 SMARCC1, SMARCD2, and ACTL6A, which encode for the essential subunits of this complex." (PMID 33837205, 2021). "For example, the exploration of the SWI/SNF complex in breast tumors revealed that ARID1A tends to be mutated in samples where neither SMARCA4, ARID2 nor SMARCA2 are mutated." (PMID 24063517, 2013).
chordoma (9 papers, 2021 to 2025). Chordomas are rare malignant tumors arising from embryonic remnants of the notochord in axial skeleton. "Despite a short median PFS, certain histological subtypes, including ASPS, chordomas, SMARCA4‐deficient tumors, gastro‐intestinal stromal tumor, and NF1 mutations, showed strong activity signals, indicating long‐term responses in some patients." (PMID 40911493, 2025). "Prolonged responses were observed in chordomas and SMARCA4‐deficient tumors." (PMID 40911493, 2025). "These mutations affect various subunits of the SWI/SNF chromatin remodeling complex, with ARID1A being the most frequently mutated gene, followed by SMARCA4, ARID1B, ARID2, PBRM1, and SMARCB1, mutations we have found to be common in adult chordoma." (PMID 39941902, 2025). "In neoplasms with pleomorphic and/or rhabdoid morphology such as SMARCB1-deficient neoplasms, SMARCA4-deficient neoplasms, malignant SFT, and CCS, a diagnosis of large cell NEC was proposed, while a NET diagnosis was discussed in the chordoma case and two of the CCSs." (PMID 34350470, 2021).
NUT carcinoma (9 papers, 2021 to 2025). "We believe that the 18F-FDG PET/CT features of NUTM1-rearranged lung sarcoma resemble those of NUT carcinoma and SMARCA4-deficient NSCLC." (PMID 41001035, 2025). "SMARCB1-deficient carcinoma, SMARCA4-deficient carcinoma and NUT carcinoma were devoid of CD8+ TILs." (PMID 36140305, 2022). "The three cases SMARCB1-deficient carcinoma, SMARCA4-deficient carcinoma and NUT carcinoma may be given special attention." (PMID 36140305, 2022). "Both SMARCA4-UT and primary pulmonary nuclear protein of testis (NUT) carcinoma are extremely aggressive undifferentiated or poorly differentiated neoplasms." (PMID 38347129, 2024). "Unfortunately, for PD-SNSCC, SMARCB1-deficient carcinoma, SMARCA4-deficient carcinoma and NUT carcinoma, no follow-up data were available." (PMID 36140305, 2022). "The one case of SMARCB1-deficient carcinoma was also PD-L1 positive, while SMARCA4-deficient carcinoma and NUT carcinoma showed no expression." (PMID 36140305, 2022). "Our cohort included one case each of SMARCB1-deficient carcinoma, SMARCA4-deficient carcinoma and NUT carcinoma, unfortunately without follow-up information." (PMID 36140305, 2022).
endometrial carcinoma (8 papers, 2018 to 2025). A malignant tumor arising from the epithelium that lines the cavity of the uterine body. "In endometrial carcinomas, SMARCA4 deficiency is associated with a dedifferentiated or anaplastic phenotype." (PMID 39888726, 2025). "Instead, their profile overlaps with SMARCA4-deficient undifferentiated endometrial carcinoma." (PMID 37686505, 2023). "Recent studies showed inactivation of SWI/SNF complex subunits such as INI1 (SMARCB1), BRG1 (SMARCA4) and ARID1A (BAF250a) whose alterations might help distinguish poorly (grade 3) differentiated endometrial carcinoma from DEAC." (PMID 29545232, 2018).
Hyperglycemia (8 papers, 2013 to 2026). An increased concentration of glucose in the blood. "The SMARCA4 gene, through the BRG1 protein, is part of the SWI/SNF chromatin-remodeling complex, which regulates gene expression and has been shown to cause pancreatic hypoplasia, glucose intolerance, hyperglycemia, and impaired insulin secretion in mice when specifically knocked out in β cells." (PMID 41306972, 2025).
lymph node metastasis (8 papers, 2013 to 2025). "Higher Brg1 (also known as SMARCA4) expression has been linked to distant and lymph node metastasis in GC patients." (PMID 39749199, 2024). "Furthermore, SMARCA4-UT more often presented with local invasion into adjacent structures and more extensive lymph node metastasis (proportion with metastasis in ≥5 lymph node stations: 55.56% vs 27.50%)." (PMID 41777060, 2025). "In patients with SMARCA4‐dNSCLC who did not have distant metastases, we found that patients with stage N2 or N3 lymph node metastases had a poor prognosis." (PMID 37184108, 2023). "In SMARCA4‐dNSCLC patients without distant metastases (stage I–III), patients with stage N2 or N3 lymph node metastases (HR: 6.35; 95% CI: 1.07–37.47) had a poor prognosis." (PMID 37184108, 2023).
myocardial infarction (8 papers, 2017 to 2026). Gross necrosis of the myocardium, as a result of interruption of the blood supply to the area, as in coronary thrombosis. "While ZFHX3 has been implicated in the pathophysiology of obesity, SMARCA4 has been shown to regulate cholesterol levels, suggesting that the methylation of both genes could be essential biomarkers of myocardial infarction risk." (PMID 40076974, 2025). "Given that myocardial infarction and small intestinal cancer occur more frequently among CD patients, SMARCA4 is a good CD candidate gene for the 19p13 locus." (PMID 33362776, 2020). "SMARCA4 is part of the chromatin remodeling complex SWI/SNF with transcriptional regulation effects and is implicated with diseases such as myocardial infarction and the self-renewal capacity of cancer cells, in which it plays a direct role in sustaining oncogenic transcriptional activity." (PMID 33362776, 2020).
cardiomyopathy (7 papers, 2013 to 2023). A disease of the heart muscle or myocardium proper. "Emerging data, however, indicate that depletion of Smarca4 levels in postnatal cardiomyocytes by adenoviral-based siRNA knockdown or dual genetic KO strategy with Smarca2 causes lethal cardiomyopathy in mice." (PMID 36656640, 2023).
cervical carcinoma (7 papers, 2012 to 2022). A carcinoma arising from either the exocervical squamous epithelium or the endocervical glandular epithelium. "Alternatively, SMARCA4 overexpression in cervical cancer cell lines leads to increased ROCK1 and stress fiber formation, which is reversible upon SMARCA4 knockdown." (PMID 24622842, 2014).
esophageal cancer (7 papers, 2014 to 2024). A primary or metastatic malignant neoplasm involving the esophagus. "Undifferentiated carcinoma of the esophagus with SMARCA4 and/or SMARCA2 deficiency is a rare tumor associated with a very poor prognosis." (PMID 38656564, 2024). "We highlight the relevance of SMARCA4 as a drug target in esophageal cancer using an engineered ESCC cell model harboring a SMARCA4 allele amenable to targeted proteolysis and identify SMARCA4-dependent cell models with low or absent SMARCA2 expression from additional tumor types." (PMID 31406271, 2019). "Similarly, in esophageal cancer models, we identified a significant association between mutation of the chromatin remodeling factor gene SMARCA4 and dependency upon the bromodomain protein BRD4 (p = 6 × 10−3), previously identified as a protein interaction partner of SMARCA4." (PMID 26947069, 2016).
Ewing sarcoma (7 papers, 2019 to 2024). A small round cell tumor that lacks morphologic, immunohistochemical, and electron microscopic evidence of neuroectodermal differentiation. "Here, we report the first case of extraskeletal Ewing sarcoma in a young female patient with a germline pathogenic variant of SMARCA4 (c.3546 + 1G>A), diagnosed with next generation sequencing (NGS)." (PMID 39439958, 2024). "Additionally, to better understand the association between SMARCA4 variants and extraskeletal Ewing sarcoma, further validation in larger cohorts is required." (PMID 39439958, 2024). "A total of 13/31 (42%) of the MN-NE showed EWSR1-related gene fusions (6 Ewing sarcomas, 5 clear cell sarcomas, and 1 desmoplastic small round cell tumor, 1 neoplasm with FUS-CREM gene fusion) and 7 (23%) were SWI/SNF (SMARCB1 or SMARCA4)-deficient neoplasms." (PMID 34350470, 2021). "VUS were also detected in NF1 in a patient without clinical symptoms of NF1, BRCA2 in a patient with nephroblastoma, SMARCA4 in a patient with Ewing sarcoma, and SEC23B, a candidate gene for Cowden, in a patient with multiple tumours and an additional pathogenic heterozygous RECQL4 variant." (PMID 37507557, 2023).
Intellectual disability (7 papers, 2015 to 2024). "Previous analysis of genotype-phenotype correlation in CSS patients, SMARCA4 variants had been shown to be associated with organ-related dysfunction, intellectual disability, developmental delay, and cancer." (PMID 39906730, 2024). "Of the genetic defects found outside the MD gene panel, seven genetic defects were found in genes present in the intellectual disability gene panel (ARID1B, SCN1A, ASPM, CTNNB, KDM6A, SMARCA4 and SETBP1)." (PMID 25735936, 2015).
metastatic melanoma (7 papers, 2009 to 2022). A melanoma that has spread from its primary site to another anatomic site. "One study found that, SMARCA4 was deficient in a significant number of primary and metastatic melanomas." (PMID 35323214, 2022). "Other studies that have looked at SMARCA4 mRNA levels have found that SMARCA4 is highly expressed especially in later stages of metastatic melanoma and that high expression is correlated with poorer survival." (PMID 35323214, 2022). "However, a different study showed that SMARCA4 is over expressed at the protein level in both primary and metastatic melanomas compared to nevi." (PMID 35323214, 2022).
small cell carcinoma (7 papers, 2019 to 2025). A neuroendocrine carcinoma composed of small malignant cells which are often said to resemble "oat cells" under the microscope. "Tumors caused by mutations in these genes include SMARCA4-deficient thoracic sarcoma, small cell carcinoma of the ovarian hypercalcemic type, and SMARCB1-deficient malignant rhabdoid tumors." (PMID 40866717, 2025). "Loss of SMARCA4 is detected in almost all small cell carcinoma of hypercalcaemic type, an aggressive ovarian neoplasm in young women." (PMID 38275587, 2023). "Clinical trials of EZH2 inhibitors in malignant rhabdoid tumours, small cell carcinoma of hypercalcaemic type, SMARCA4 deficient thoracic sarcoma, and epithelioid sarcoma are ongoing." (PMID 38275587, 2023). "The SMARCA4-deletion patient was diagnosed with synovial sarcoma of the ovary, revised to small-cell carcinoma based on this study, and would have fulfilled both criteria if the initial diagnosis had been correct." (PMID 33332384, 2020). "In this context, it has been identified a SMARCA4 gene involved in the development of small cell carcinoma of hypercalcemic type (SCCOHT), a rare and aggressive type of ovarian cancer." (PMID 31676783, 2019).
uveal melanoma (7 papers, 2018 to 2025). A melanoma derived from melanocytes of the uveal tract. "Uveal melanoma is another cancer type that is highly sensitive to treatment with allosteric SMARCA4/SMARCA2 inhibitors." (PMID 38390898, 2024). "Some uveal melanoma cell lines were highly sensitive to the depletion of SMARCA4 alone and others were only sensitive to the dual depletion of both SMARCA4 and SMARCA2." (PMID 38390898, 2024). "Recently, SF3B1 mutations in uveal melanoma (UVM), myelodysplastic syndrome (MDS), and CLL were associated with mis-splicing of Bromodomain Containing 9 (BRD9), a subunit of the non-canonical BRG1 (SMARCA4) or BRM (SMARCA2) associated factor (ncBAF) chromatin remodeling complex." (PMID 39261602, 2024).
COVID-19 (6 papers, 2022 to 2025). A disease caused by infection with severe acute respiratory syndrome coronavirus 2. "For example, SMARCA4 was identified as being targeted by lung specific eQTLs (rs10416073, rs7247198) in the severe phenotype (within the limitations COVID-19 Host Genetics Initiative definition)." (PMID 37336921, 2023). "In the local genetic correlation analysis between COVID-19 and cardiac traits that showed significant genetic correlation, we found that SMARCA4 region to have genetic correlation between COVID-19 and CAD, which was also identified by cross-trait meta-analysis." (PMID 36187959, 2022). "SMARCA4 is a well-known gene associated with CAD, and it mediated nucleosome remodeling which was considered another epigenetic mechanism that can affect the course of COVID-19." (PMID 36187959, 2022). "Notably, research from the Getx study found that rs73009538 serves as an eQTL for SMARCA4, a key component of the SWI/SNF complex that regulates immune responses and gene expression, particularly ACE2, the primary receptor for COVID-19." (PMID 40034745, 2025).
germ cell neoplasms (6 papers, 2020 to 2025). "If HVA and VMA are negative in posterior mediastinal tumors, rarer tumors, such as germ cell tumor, liposarcoma, and SMARCA4-deficient thoracic sarcoma should be considered in the differential diagnosis." (PMID 32522190, 2020). "Taken together, these very recent studies highlight the existence of two distinctive categories of aggressive malignant teratoid tumors unrelated to genuine germ cell neoplasms: one driven by SMARCA4 inactivation and another related to DICER1 mutations." (PMID 32507920, 2020).
metastatic disease (6 papers, 2015 to 2026). "In contrast to previous cases, our patient had metastatic disease at presentation, demonstrating a comparable aggressiveness to other SMARCA4‐deficient visceral neoplasms." (PMID 41550383, 2026). "Notably, none of the previously reported cutaneous cases presented with metastatic disease, in contrast to SMARCA4‐deficient visceral malignancies, which are frequently metastatic at the time of diagnosis." (PMID 41550383, 2026). "Given the known aggressiveness of SMARCA4‐deficient tumors, initial workup with PET/CT, along with comprehensive staging, is recommended to assess for metastatic disease and guide management." (PMID 41550383, 2026). "Additionally, the upstream regulator of HLF, SMARCA4, exhibited higher expression in metastatic tumors compared to primary tumors across multiple cancer types." (PMID 40473600, 2025). "Conceivably, then, SMARCA4 may contribute to the establishment or maintenance of metastatic disease, although functional studies are needed to confirm this hypothesis." (PMID 28594900, 2017).
rhabdomyosarcoma (6 papers, 2014 to 2025). A rare aggressive malignant mesenchymal neoplasm arising from skeletal muscle. "No specific SWI/SNFc aberrations characterize this tumor, but recent data support the importance of SMARCA4 expression in the maintenance of alveolar and embryonal rhabdomyosarcoma cells." (PMID 37446319, 2023). "In rhabdomyosarcoma, dual depletion of SMARCA4 and SMARCA2 by protein degradation enzymes has been shown to inhibit tumor growth." (PMID 37446319, 2023). "The SMARCA4/SMARCA2 PROTAC, ACBI1, is also reported to have some efficacy in preclinical rhabdomyosarcoma models." (PMID 40983796, 2025).